C1QTNF1 (C1q and TNF related 1)
Synonyms: GIP; CTRP1; ZSIG37; FLJ90694
Tractability: Antibody: UniProt places it where antibodies can reach, with high confidence; its Gene Ontology location is reachable by antibodies, with high confidence; UniProt predicts a signal peptide or a membrane-spanning region.
Gene: Protein-coding gene on chromosome 17 (79,022,729 to 79,049,788, forward strand). Ensembl gene ENSG00000173918.
Subcellular location: Secreted
Subcellular location (Human Protein Atlas): Cytosol; Nucleoplasm; Predicted to be secreted
Gene Ontology:
Molecular function: collagen binding; protein binding; identical protein binding
Biological process: negative regulation of platelet activation; negative regulation of platelet aggregation; positive regulation of aldosterone secretion; positive regulation of cytosolic calcium ion concentration; positive regulation of gene expression
Cellular component: extracellular region; plasma membrane
Genetic constraint (gnomAD): Loss-of-function variants: 22 observed, 26.98 expected, observed/expected ratio (o/e) 0.82, 90% interval 0.58 to 1.16. The upper end of that interval is the gene's LOEUF score, 1.16, which puts it in group 5 of 6, group 1 being the genes least tolerant of losing a copy. Missense variants: 373 observed, 393.98 expected, observed/expected ratio (o/e) 0.95, 90% interval 0.87 to 1.03. Synonymous variants: 166 observed, 157.33 expected, observed/expected ratio (o/e) 1.06, 90% interval 0.93 to 1.2.
Homologues: Orthologues: chimpanzee C1QTNF1 (98% identical), macaque C1QTNF1 (86% identical), pig C1QTNF1 (80% identical), guinea pig C1QTNF1 (80% identical), rat C1qtnf1 (78% identical), mouse C1qtnf1 (77% identical), dog C1QTNF1 (70% identical), zebrafish c1qtnf1 (58% identical), rabbit C1QTNF1 (55% identical). Paralogues in human: C1QTNF8 (43% identical), C1QTNF6 (43% identical), C1QTNF2 (24% identical), C1QTNF9 (22% identical), ADIPOQ (22% identical), C1QTNF9B (22% identical), COL10A1 (22% identical), C1QTNF5 (21% identical), OTOL1 (21% identical), C1QTNF7 (21% identical), COL8A2 (21% identical), C1QB (20% identical), and 11 more.
Diseases named in the same sentence as C1QTNF1 in open-access papers:
C1QTNF1 is named in the same sentence as 75 diseases in open-access papers, as found by Europe PMC text mining. Sharing a sentence is not in itself a finding about the gene and the disease. The quoted sentences say what the papers report.
coronary artery disease (14 papers, 2014 to 2023). "C1QTNF1 has been shown to be linked with dysregulation of lipid metabolism and an inflammatory response in macrophages, leading to coronary artery disease." (PMID 35945262, 2022). "Other proteins associated with incident HF in our research have been linked to coronary heart disease (ANG, C1QTNF1 and CCL3) and thromboembolism (SERPINA5) with the potential to induce myocardial damage." (PMID 35945262, 2022).
Obesity (14 papers, 2014 to 2025). Accumulation of substantial excess body fat. "In participants who mostly remained with obesity despite conventional (non-surgical) anti-obesity measures, C1QTNF1, FGF-21 and CST3 were associated with a significantly higher risk of HF compared with those who lost weight through surgical intervention." (PMID 35945262, 2022). "Three proteins (C1QTNF1, FGF-21 and CST3) were associated with incident HF among patients without bariatric surgery who retained excess body fat, suggesting that dyslipidemia and chronic kidney disease may constitute therapeutic targets to prevent the development of HF among patients with obesity." (PMID 35945262, 2022). "Three proteins, C1QTNF1, FGF-21 and CST3, reflecting dyslipidemia and kidney disease, displayed a higher association with HF in patients who did not undergo weight-loss-surgery and maintained with obesity." (PMID 35945262, 2022).
atherosclerosis (10 papers, 2015 to 2025). A disease characterized by the build-up of fatty material and calcium deposition in the arterial wall resulting in partial or complete occlusion of the arterial lumen. "The transcript encoded by the C1QTNF1 gene plays a role in the dysregulation of lipid metabolism and inflammatory responses in macrophages during the development of atherosclerosis." (PMID 39126078, 2024).
glioblastoma (6 papers, 2019 to 2023). The most malignant astrocytic tumor (WHO grade IV). "Among them, C1QTNF1 expression levels were increased in several tumor tissues, including Lymphoid Neoplasm Diffuse Large B-cell Lymphoma (DLBC), Glioblastoma multiforme (GBM), Head and Neck squamous cell carcinoma (HNSC), and KIRC." (PMID 37529377, 2023).
lung carcinoma (3 papers, 2022 to 2025).
cardiac hypertrophy (2 papers, 2021 to 2025). "C1QTNF1 exhibited a trend of differential expression in human smooth muscle cells and was found to accelerate cardiac hypertrophy and fibrosis in cardiomyocytes." (PMID 40266928, 2025).
COVID-19 (2 papers, 2020 to 2022). A disease caused by infection with severe acute respiratory syndrome coronavirus 2. "The anticoagulant C1QTNF1 regulates blood coagulation, a well-described complication in COVID-19 patients." (PMID 36405747, 2022). "According to these criteria, we found four procoagulants (ADAMTS13, F11, HGFAC, KLKB1) and two anticoagulants (C1QTNF1, SERPINA5), whose expression may predispose males and older individuals to COVID-19-related coagulopathy and severe COVID-19 disease." (PMID 32751741, 2020).
hepatocellular carcinoma (2 papers, 2022 to 2024). A malignant tumor that arises from hepatocytes. "Compared with THLE-2 cells, C1QTNF1 was found to be significantly downregulated in all hepatoma cell lines." (PMID 38498315, 2024). "We examined the expression profile of C1QTNF1 in the human hepatocyte cell line THLE-2 and four hepatoma cell lines (Huh7, Hep3B, SNU398, and SNU449)." (PMID 38498315, 2024).
metastatic cancer (2 papers, 2022 to 2024). A carcinoma which has spread from the original site of growth to another anatomic site. "C1q and TNF-related 1 (C1QTNF1, also known as CTRP1) expression is upregulated in metastatic cancer, high CTRP1 level is connected with poor prognosis, and CTRP1 knockout inhibits cell proliferation and invasion, and tumor growth." (PMID 38586328, 2024).
Stroke (2 papers, 2021 to 2023). Sudden impairment of blood flow to a part of the brain due to occlusion or rupture of an artery to the brain. "Six proteins (AGFG2, C1QTNF1, CHIT1, DNAJC15, FTL, and OLR1) have been reported to be implicated in other neurodegenerative diseases such as AD, ALS, or stroke, but not in PD." (PMID 37422510, 2023).
Bladder Urothelial Carcinoma (1 paper, 2023). "Kaplan-Meier survival curves showed that high expression of C1QTNF1 was significantly associated with a worse prognosis in Bladder Urothelial Carcinoma (BLCA), Brain Lower Grade Glioma (LGG), KIRC, and Uveal Melanoma (UVM)." (PMID 37529377, 2023).
colon adenocarcinoma (1 paper, 2023). "Meanwhile, we investigated the expression levels of C1QTNF1 in paired tumor tissues and normal tissues in the TCGA dataset and found that the expression levels of C1QTNF1 were increased in Colon adenocarcinoma (COAD), HNSC, and KIRC." (PMID 37529377, 2023).
leiomyoma (1 paper, 2024). A well-circumscribed benign smooth muscle neoplasm characterized by the presence of spindle cells with cigar-shaped nuclei, interlacing fascicles, and a whorled pattern. "Of the 7 pQTL found proximal to rs78378222, C1QTNF1 (complement C1Q tumor necrosis factor-related protein 1) was also found to be significantly downregulated in leiomyoma relative to myometrium in 2 independent UF RNA-seq datasets." (PMID 38326302, 2024).
ovarian carcinoma (1 paper, 2009). A malignant neoplasm originating from the surface ovarian epithelium. "RT-PCR analyses of ovarian cancer samples validated gene expression profiles of TMEM158, GBE1 and HEG1 from a chromosome 3 transcriptome analysis and IGFBP4, PTRF and C1QTNF1 from a chromosome 17 transcriptome analysis." (PMID 19580657, 2009).
tumor (11 papers, 2019 to 2024). "Since tumor formation is potentially reversible at the tipping point, we utilized adeno-associated virus 9 to deliver C1QTNF1 (AAV9-C1QTNF1) mRNA sequence and induce overexpression of C1QTNF1." (PMID 38498315, 2024). "RBP3, associated with the CM of myeloid cells and phagocytes, and C1QTNF1, associated with the activation of platelets, played key roles towards metastasis in the tumor microenvironment." (PMID 34068397, 2021). "Our study analyzed the association between C1QTNF1 expression and tumor immune cell infiltration." (PMID 37529377, 2023). "Through both in vitro and in vivo experiments, we discovered that C1QTNF1 possesses the ability to inhibit tumor growth." (PMID 38498315, 2024). "The results revealed that C1QTNF1 mRNA expression levels in tumor tissues were lower compared to those in non-tumor tissues." (PMID 38498315, 2024). "The group with inducible C1QTNF1 expression developed smaller tumor volumes compared to the control group." (PMID 38498315, 2024). "In both cell and mouse models, overexpression of C1QTNF1 can significantly suppress tumor growth and reduce the invasive and migratory capabilities of the tumor." (PMID 38498315, 2024). "To further verify the role of C1QTNF1 as a tumor suppressor, we induced overexpression of C1QTNF1 in Huh7 and SNU449 cells using a lentiviral vector." (PMID 38498315, 2024). "In this study, we analyzed the expression of C1QTNF1 in normal and tumor tissues from the TCGA and GTEx datasets and found that C1QTNF1 was upregulated in multiple tumor tissues." (PMID 37529377, 2023). "Through correlation analysis, expression level analysis and prognostic analysis, we found that hsa-miR-27b-3p was the most likely upstream tumor suppressor miRNA of C1QTNF1." (PMID 37529377, 2023). "By comparing the expression of C1QTNF1 in unpaired and paired KIRC tumor tissues and normal tissue samples, we found that the expression level of C1QTNF1 was significantly increased." (PMID 37529377, 2023). "We hypothesize that C1QTNF1 as an adipokine may also play a deleterious role in driving KIRC tumor progression." (PMID 37529377, 2023). "Both in vitro and in vivo studies showed that C1QTNF1 could inhibit tumor growth." (PMID 38498315, 2024). "This suggests that C1QTNF1 may be involved in the process of tumor immunity." (PMID 37529377, 2023). "We propose C1QTNF1 as a prognostic biomarker for HCC, potentially influencing tumor development through a platelet-related cancer signaling pathway." (PMID 38498315, 2024). "Firstly, we assessed the mRNA expression of C1QTNF1 in both tumor and adjacent non-tumor tissue samples from 37 HCC patients." (PMID 38498315, 2024). "Knockdown of C1QTNF1 in A549 and HCT116 resulted in tumor cell proliferation, invasion, and growth." (PMID 37529377, 2023). "MSGN1, ISM2, HAS1, RETN, MMP19, C1QTNF1, and F13A1 were all involved in the regulation of tumors, but their involvement in the regulation of tumor immunity is not clear." (PMID 34177903, 2021).
cancer (5 papers, 2019 to 2024). A tumor composed of atypical neoplastic, often pleomorphic cells that invade other tissues. "Furthermore, our research indicated that platelet-expressed C1QTNF1 is involved in cancer-associated signaling pathways." (PMID 38498315, 2024). "The findings revealed that C1QTNF1 expression is higher in platelets from HCC patients compared to those from healthy controls, suggesting a role for C1QTNF1 in platelet-related cancer signaling pathways." (PMID 38498315, 2024). "The authors evaluated the expression levels of C1QTNF1 mRNA in 33 different cancer tissues and normal tissues using TCGA and GTEx data." (PMID 37529377, 2023). "Analysis on the GEPIA2 website showed that high expression of C1QTNF1 can lead to a poor prognosis in patients with a variety of cancers." (PMID 37529377, 2023). "Next, in examining the relationship between the initiation of biological functions enriched by C1QTNF1 and its inverse DEGs before and after the critical period of HCC formation initiation, we observed enrichment in most typical cancer-related pathways." (PMID 38498315, 2024). "C1q And TNF Related 1 (C1QTNF1), a novel adipokine and member of the C1q and TNF-related protein (CTRP) family, has been shown to affect the progression of various cancers." (PMID 37529377, 2023). "Furthermore, C1QTNF1 presents a novel therapeutic target in HCC treatment, operating through the platelet-related cancer signaling pathway." (PMID 38498315, 2024).
C1QTNF1 also shares sentences with these, for which no sentence is quoted: diabetes (14 papers); Insulin resistance (13); type 2 diabetes mellitus (13); dyslipidemia (8); Hypertension (8); metabolic disease (6); cardiovascular diseases (5); Hyperglycemia (5); congestive heart failure (4); chronic kidney disease (3); heart failure (3); Sepsis (3); coronary artery stenosis (2); Hepatic steatosis (2); ischemic stroke (2); kidney disease (2); myocardial infarction (2); adenoma (1); age-related macular degeneration (1); bone osteosarcoma (1); brain injury (1); Cerebral ischemia (1); cholestasis (1); coagulopathy (1); coronary atherosclerosis (1); endothelial dysfunction (1); essential hypertension (1); gestational diabetes mellitus (1); gingivitis (1); Glucose intolerance (1).
A further 29 diseases each share a sentence with C1QTNF1 in 1 paper.